EZH2 (enhancer of zeste 2 polycomb repressive complex 2 subunit)
Diseases named in the same sentence as EZH2 in open-access papers (continued):
Sharing a sentence is not in itself a finding about the gene and the disease.
prostate carcinoma (continued). "Importantly, we show in the same setting that inhibition of EZH2 protein substantially blocked the castration-induced polarization change towards M2, uncovering a thus far underappreciated role for EZH2 in macrophage polarization another rationale towards co-targeting AR and EZH2 in prostate cancer." (PMID 34857732, 2021). "EZH2, SUZ12, and EED gene amplification was most frequently found in prostate cancer, whereas lymphoid malignancies (DLBCL) frequently showed EZH2 mutations." (PMID 34202528, 2021). "The following mechanism is likely: EZH2 inhibits FOXO1 expression and may serve as a target of EZH2 inhibitors, which can be used to overcome EZH2 inhibitor resistance in PTEN mutant cancers or to treat PTEN-deficient prostate cancer in combination with taxane." (PMID 34149432, 2021). "In accordance with tissue origin data, the majority of alterations in the EZH2, SUZ12, and EED genes in prostate cancer are represented by amplifications." (PMID 34202528, 2021). "For final validation of the function mechanism of SChLAP1/EZH2 in prostate cancer tumorigenesis, we established the CDX model by subcutaneous injection on nude mice with cultured prostate cancer cells." (PMID 33589600, 2021). "Overall, EZH2 inhibition increased CD4+ and CD8+ tumor infiltration in mice and potentiate prostate cancer response to anti-PD-1 therapy." (PMID 34262562, 2021). "In contrast, TR4 was demonstrated to promote prostate cancer metastasis via CCL2 and EZH2 signaling." (PMID 34616769, 2021). "Here, we show that amplification and higher expression of EZH2 and EED correlate with poor survival, further supporting the involvement of EZH2 and its PRC2 protein partners in prostate cancer." (PMID 34202528, 2021). "Up to now, the research on EZH2 inhibitor GSK126 had made notable progress in different kinds of cancers, including prostate cancer cells and gastric cancer cells." (PMID 34737956, 2021). "Second, EZH2 directly binds to the promoter of prostate-specific antigen, an AR-targeted gene, and inhibits its expression in CAB-resistant prostatic cancer cells." (PMID 35186711, 2021). "When human prostate cancer cell lines DU145 and PC3 were treated with silibinin, expression of EZH2, SUZ12, and EED was downregulated, accompanied by an upregulation of H3K27me3 methylation." (PMID 34235089, 2021). "A similar cell growth inhibition effect is observed in DU145 and PC3 cells transfected by a siRNA targeting EZH2, the histone methyltransferase of the PRC2 complexes which is up-regulated in prostate cancers." (PMID 32256978, 2020). "Our integrative mechanism dissection revealed that TROAP is in a pathway downstream of EZH2 and that it activates the TWIST/c-Myc pathway to regulate prostate cancer progression." (PMID 33692939, 2020). "There is a positive correlation between lncRNA MALAT1 and EZH2 expression in human castration-resistant prostate cancer tissues, in which the knockdown of lncRNA MALAT1 impairs EZH2 recruitment and upregulates expression of EZH2-repressed genes." (PMID 31830649, 2020). "Enhancer of Zeste 2 (EZH2), the enzymatic component of PRC2 that methylates of lysine 27 at histone H3, is often overexpressed in prostate cancer." (PMID 32155117, 2020). "Lineage transformation and therapeutic resistance in our prostate cancer models were dependent on increased expression of stem cell reprogramming factors like SOX2 and EZH2." (PMID 32292420, 2020). "To determine which of the three genes plays the key role in prostate cancer, we performed a principal component analysis (PCA) using the TCGA_PRAD and the results showed that EZH2 plays a more important driving role in prostate cancer." (PMID 33692939, 2020). "Recently, it was revealed that EZH2, through H3K27 methylation, suppressed the expression of SERPINB1, which in turn promoted inflammation-mediated prostate cancer progression." (PMID 32371945, 2020).
prostate carcinoma (continued). "EZH2 can directly inhibit the miR-29, miR-181, and miR-200 families, which in turn target EZH2 and other PRC2 proteins in B-cell lymphomas and prostate cancer." (PMID 32635336, 2020). "In a recent study the authors found that EZH2 binds to the HNF1B locus and suppresses the HNF1B gene expression in prostate cancer cell lines, with a reverse correlation between EZH2 and HNF1B expression." (PMID 32873863, 2020). "CENPA expression tracks tightly with a number of previously identified prostate cancer pathogenesis factors including CENPF, UBE2C, and EZH2 (and Data Set S1)." (PMID 32371391, 2020). "Consistently, restored HNF1B expression significantly suppresses EZH2-mediated overgrowth and EMT processes, including migration and invasion of prostate cancer cell lines." (PMID 31636385, 2020). "Our findings elucidate a previously underappreciated path of EZH2 exerting its oncogenic effects through repressing HNF1B and promoting SLUG mediated EMT process in prostate cancer." (PMID 31636385, 2020). "Inhibition of EZH2 and BRCA1 in experimental models of prostate cancer induces an increase of cancer stem cell properties." (PMID 31366128, 2019). "EZH2 is activated by ADT and PKA-CREB1 signaling, which in turn induces NE markers and reduces TSP1 in prostate cancer cells." (PMID 32039001, 2019). "Overexpression of EZH2 and elevated PRC2 activity promote prostate cancer cell proliferation and migration." (PMID 32039001, 2019). "Experimentally, high N-Myc levels lead to shift of different prostate cancer models and of PTEN-negative mouse organoids towards androgen independence by strengthening the EZH2 and AKT signaling axis." (PMID 31200487, 2019). "We further explored the clinical relevance of EZH2 and FOXO1 expression in an independent cohort of prostate cancer patient specimens (n = 42) using IHC." (PMID 31410199, 2019). "Immunohistochemistry was employed to assess the correlation between EZH2 and FOXO1 protein expression in prostate cancer patient specimens." (PMID 31410199, 2019). "H3K27me3 levels are determined by histone methyltransferase EZH2 (enhancer of zeste homolog 2) and histone demethylase JMJD3 (jumonji domain-containing 3), and both these proteins are upregulated in prostate cancer." (PMID 29805743, 2018). "Gene set expression was also evaluated on prostate cancer cell lines (DU 145, PC-3 and LNCaP) treated with an inhibitor of JMJD3 (GSK-J4) or EZH2 (DZNeP) to study their involvement in gene regulation." (PMID 29805743, 2018). "In particular, SOX4 regulates EZH2 expression and chromating remodeling, and is a key component of the PI3K/AKT pathway in prostate cancer." (PMID 29888169, 2018). "Further supporting the existing of an EZH2/TSP1 axis in human prostate cancers, we found that TSP1 and EZH2 are expressed significantly lower and higher, respectively, in metastatic CRPC than in localized prostate cancers (Grasso_mCRPC39)." (PMID 30287808, 2018). "In human prostate cancer cells, DANCR binds to EZH2 and inhibits the expression of TIMP-2 by epigenetic silencing." (PMID 29416741, 2018). "Consistent with the literature, treating LNCaP cells with MDV3100 or culturing another AR-positive prostate cancer cell line 22Rv1 in CSS medium has resulted in induction of H3K27me3 and NE markers, which suggests that ADT activates EZH2’s PRC2 activity." (PMID 30287808, 2018). "MYC proteins also drive epigenetic activation of gene expression in prostate cancer; the PRC2 member EZH2 is directly upregulated by MYC and MYCN, which was shown to be a driver of NEPC by inducing an EZH2-mediated transcriptional program." (PMID 29888169, 2018). "In this study, we have uncovered functional connections among ADT, CREB activation, EZH2-mediated epigenetic repression, NE phenotypes, TSP1 expression, and angiogenesis in prostate cancer cells." (PMID 30287808, 2018).
prostate carcinoma (continued). "Our findings elucidate diverse hypoxia-regulated pathways including EZH2-mediated hypermethylation and miR-93-induced silencing contribute to attenuation of TGFBR2 expression and promote cancer progression in prostate cancer." (PMID 29699590, 2018). "Consistently, mRNA expressions of EZH2 and TSP1 negatively correlate with each other in human prostate cancers, such as in Grasso_mCRPC (Spearman Correlation Rho = −0.55, P ≤ 1E-6) and in Beltran_NEPC (Rho = −0.53, P ≤ 8E-5)." (PMID 30287808, 2018). "Taken together, our data propose a new model of prostate cancer progression, where ADT and beta adrenergic signaling concordantly regulate PKA/CREB activation, EZH2 activity, TSP1 expression, angiogenesis, NED, and NEPC progression." (PMID 30287808, 2018). "In summary, we found that miR-193a is downregulated in metastatic prostate cancer and plays tumor suppressive function in prostate cancer, which was attributed to HOTAIR mediated EZH2 targeting to the promoter of miR-193a." (PMID 29141691, 2017). "Further study proved that the let-7 family can bind to the 3’ untranslated region (UTR) of the EZH2 mRNA to decrease EZH2 expression, leading to repression of CSC self-renewal ability in prostate cancer." (PMID 28415635, 2017). "At specific loci, the histone methyltransferase enhancer of zeste homolog 2 (EZH2), a subunit of PRC2, catalyzes H3K27 trimethylation, leading to chromatin compaction and subsequently silencing of genes in prostate cancer." (PMID 28403887, 2017). "MiR-141 regulated MEG3 expression through repression of EZH2 expression, a subunit of the polycomb repressor complex 2 (PRC2), in prostate cancer." (PMID 29287592, 2017). "Mechanistically, we found that TIMP2/3, which are critical metastasis inhibitor of prostate cancer, were down-regulated by DANCR synergistically with EZH2 through epigenetically silencing their promoter by chromatin immunoprecipitation assay." (PMID 27191265, 2016). "In summary, this is the first report that both AR and EZH2 regulate RUNX1 and that RUNX1 was shown to have differential functions in androgen-dependent and androgen-independent prostate cancer cells." (PMID 25537508, 2015). "The fact that EZH2 and SEM3A3 are inversely expressed in vivo is supported by previous data in mouse haematopoietic stem cells and human prostate cancer." (PMID 26043758, 2015). "Enhancer of zeste homolog 2 (EZH2), which is a major contributor to androgen-independent signaling in prostate cancer, represses RUNX1 transcription, and the expression of RUNX1 is negatively associated with EZH2 in clinical samples." (PMID 25537508, 2015). "By investigating the histone modification of genes in prostate cancer, we found that the RUNX1 promoter is occupied with H3K27me3 and that EZH2 is bound to the region." (PMID 25537508, 2015). "Combination of the Top2 poison etoposide with the Ezh2 inhibitor GSK126 or DZNep significantly increased cell death in vitro in murine and human prostate cancer cell lines." (PMID 25605014, 2015). "In fact, to study histone methylation, a selection of six genes involved in prostate cancer was made, including RAR beta 2, ER alpha, PGR, RGMA, EZH2, and SRC3." (PMID 25535400, 2014). "Our study is corroborated through Oncomine co-expression analysis that shows CtBP1, EZH2 and P4HA1 are co- and over-expressed in prostate carcinoma samples." (PMID 25115393, 2014). "EZH2 can induce EMT and increase the metastatic potential of prostate cancer cells by downregulation of DAB2IP, a tumor-suppressive Ras GTPase-activating protein (RasGAP)." (PMID 25277175, 2014). "DNA chromatin remodeling proteins, such as EZH2, SUZ12, and DNMT3a, were also under-expressed, as observed in prostate cancer studies." (PMID 24504051, 2014). "Although DAB2IP is often epigenetically down regulated by EZH2 activation in many tumors, we defined a novel pathway of functionally inactivating DAB2IP in prostate cancer cells through Akt activity." (PMID 24912918, 2014).
prostate carcinoma (continued). "EZH2 is also targeted by the let-7 family of microRNAs and prostate cancer cells pretreated with BR-DIM displayed an up-regulated let-7 family and down-regulated EZH2 expression." (PMID 24739220, 2014). "Based on the overall results, we believe in a direct role of EZH2 in silencing of RAR beta 2, ER alpha, PGR, and RGMA genes via H3K27me3 mark in prostate cancer and therefore indicates adverse prognosis." (PMID 25535400, 2014). "Together, results from prostate cancer cell lines and prostate tissue suggested that ID4 is regulated in part by histone modifications in an EZH2 dependent manner." (PMID 25115397, 2014). "However, it may require further investigation about the direct feature of the interaction because a polycomb group protein EZH2 was also shown to interact directly with both ERα and β-catenin, thus connecting the estrogen and Wnt signaling circuitries in breast and prostate cancer cells." (PMID 24340027, 2013). "Here, we show that EZH2 plays an active role in this process by repressing the expression of TIMP2 and TIMP3 in prostate cancer cells." (PMID 22272343, 2012). "EZH2 knockdown markedly reduces the proteolytic activity of MMP-9, thereby decreasing the invasive activity of prostate cancer cells." (PMID 22272343, 2012). "Thus, TIMP3 may be a target of EZH2 for repression in prostate cancer cells." (PMID 22272343, 2012). "To verify specific associations between miR-26a and miR-26b and their predicted binding site on the EZH2 3′UTR in prostate cancer cells, we cloned the 3′UTR of EZH2 into a luciferase reporter vector." (PMID 21941025, 2011). "In our set of matched primary prostate cancer specimens and normal prostate tissue, we found MYC and EZH2 elevation, and a positive correlation between the expression of the two genes." (PMID 21941025, 2011). "While EZH2 elevation is most marked in advanced/castrate resistant metastatic lesions, EZH2 is also very commonly overexpressed in almost all human PIN and early prostate cancer lesions." (PMID 21941025, 2011). "Hence, Myc overexpression may drive prostate cancer initiation by perturbing normal prostate differentiation programs and aberrantly activate embryonic stem-cell like programs, in part by the induction of EZH2." (PMID 21941025, 2011). "Next, we probed the functional relationship between ERG and EZH2 and the possibility of direct regulation of EZH2 by ERG in prostate cancer cells, in which we experimentally up- and down-regulated ERG." (PMID 20479932, 2010). "Collectively, these data indicated that both EZH2 and NKx3.1 mediated relevant effects of ERG and ESE3 in prostate cancer cells." (PMID 20479932, 2010). "Some of these genes have known functions in prostate cancer, such as FGFR1, BCL2, HOXC5, HOXA4, TWIST1, EZH2, KLF4, CTGF." (PMID 19262738, 2009). "ERG and EZH2 interact physically, and this functional ERG-EZH2 interaction enhances ERG transcriptional activity, producing profound changes in the transcriptional activity of prostate epithelial cells and sustaining prostate cancer progression." (PMID 40332527, 2025). "The enzyme enhancer of zeste homolog 2 (EZH2) is known for its role in transcriptional repression through histone modification, and its overexpression is the culprit for the progression and immune evasion of “cold” prostate cancer (PCa)." (PMID 40672434, 2025). "Prostate cancer may exhibit reduced aggressiveness upon termination of DNMT1 expression, as this leads to a corresponding decrease in Enhancer of Zeste Homologue (EZH2) expression." (PMID 40034825, 2025). "EZH2 can epigenetically silence the dysfunctional homology interaction protein (DAB2IP), a tumor suppressor involved in regulating Ras and NF-κB pathways, thereby driving tumorigenesis and metastasis in prostate cancer." (PMID 40959108, 2025). "EZH2, the catalytic subunit of PRC2, functions as an oncogene in prostate cancer." (PMID 40959108, 2025).
prostate carcinoma (continued). "EZH2, as the catalytic core subunit of PRC2, is markedly overexpressed in prostate cancer." (PMID 40959108, 2025). "Moreover, lncRNA-p21 augments the methylation of STAT3 by enhancer of zeste homolog 2 (EZH2), leading to prostate cancer neuroendocrine transdifferentiation." (PMID 38544804, 2024). "After subjecting PC-3 prostate cancer cells to TPL treatment, we observed an upregulation in the mRNA expression levels of specific target genes (ADRB2, DAB2IP and CDKN2A) that are under negative regulation by EZH2." (PMID 38678240, 2024). "EZH2, a HMT at H3K27 site and the subunit of polycomb repressor complex 2 (PRC2), is widely acknowledged to be overexpressed in multiple types of cancer, mainly showing high expression in NE prostate cancer." (PMID 39372390, 2024). "EZH2 is an emerging therapeutic target in advanced prostate cancer yet clinical biomarkers of response have not been established." (PMID 38405800, 2024). "Indeed, treating several prostate cancer cell lines with GSK126, an inhibitor of EZH2, resulted in REST induction and reduced NE marker ENO2 expression." (PMID 38777812, 2024). "Given that we have illustrated that REST is a direct target of EZH2 in NEPC cells, next, we set out to determine the genetic relations of the three proteins on this CREB1-EZH2-REST pathway in the context of ADT-induction of NE markers in prostate cancer cells." (PMID 38777812, 2024). "Notably, ADT-activated CREB1 signaling enhances EZH2’s epigenetic repression of REST, which in turn induces NE markers in prostate cancer cells." (PMID 38777812, 2024). "Imatinib may have potential applications in prostate cancer treatment, as it can induce resistance by recruiting DNMT3A and EZH2 to the promoter region of PTEN in leukemia patients, thereby downregulating the transcription of this gene." (PMID 39309810, 2024). "To investigate whether there is an interaction between EZH2 and WNT5A in prostate cancer, we transfected C4-2B EnzR cells with siEZH2, siSFRP1, and their negative controls." (PMID 38566211, 2024). "Later studies found that phosphorylation at S21 not only suppressed canonical enzymatic activity, but was required for non-canonical, H3K27me3-independent functions of EZH2 in prostate cancer and glioblastoma models." (PMID 37664059, 2023). "Notably, EZH2 and HDAC inhibitors also triggered tumor regression in an immunocompetent mouse model of AR-independent prostate cancer, PT-09, indicating that this combination remains effective in the context of an intact immune system." (PMID 37104245, 2023). "Since LNCaP cells do not express PTEN, we used the prostate cancer cell line, VcaP, to compare the effects of INPP4B and PTEN loss on EZH2 protein levels." (PMID 38001678, 2023). "To characterize the phenotypes of the epithelium in PCaT and normal prostate tissue and in derived early and late PCCs and PDOs, we assessed the expression of basal (CK5, p63) and luminal (CK18, AR1) epithelial markers and prostate cancer markers (AMACR and EZH2) by RT-PCR." (PMID 36769153, 2023). "For instance, in prostate cancer LNCaP cells, ATAD2 affects the recruitment of histone methylase mixed lineage protein-1 (MLL1) and RNA polymerase II during enhancer of zeste homologue 2 (EZH2) gene transcription." (PMID 36632213, 2023). "In vitro and animal studies have indicated that EZH2 inhibitors, such as GSK343, could be a promising therapy for prostate cancer with neuroendocrine differentiation." (PMID 37240468, 2023). "As we excepted, compared to its reversible analog, IHMT-337 exerts high potency in malignancies in which EZH2 functions as a non-methyltransferase, such as breast and prostate cancer." (PMID 36642705, 2023). "Although Sox2, EZH2, and Oct4 are not used as prostate cancer stem cell markers, more and more studies confirmed the regulatory roles of these genes in PCSC." (PMID 35342431, 2022).